DUX4L7 (double homeobox 4 like 7 (pseudogene))
Description:
May be involved in transcriptional regulation.
Gene: Unprocessed pseudogene on chromosome 4 (190,071,232 to 190,072,506, forward strand). Ensembl gene ENSG00000281652.
Subcellular location: Nucleus